MYRF (myelin regulatory factor)
Diseases named in the same sentence as MYRF in open-access papers (continued):
Sharing a sentence is not in itself a finding about the gene and the disease.
congenital heart disease (4 papers, 2018 to 2023). A heart disease that is present at birth. "Notably, all four patients with MYRF variants also had congenital heart disease (CHD), and three of them had genital anomalies including blind-ending vagina in a female and ambiguous genitalia or undescended testes in two male cases." (PMID 30532227, 2018). "We identified DMRs overlapping MYRF and ATP11A which are both genes directly associated with congenital heart disease including BAV." (PMID 35711915, 2022). "Common phenotypes of MYRF de novo variant carriers include CDH, congenital heart disease and genitourinary abnormalities, suggesting that it represents a novel syndrome." (PMID 30532227, 2018).
scimitar syndrome (4 papers, 2018 to 2023). Scimitar syndrome is characterized by a combination of cardiopulmonary anomalies including partial anomalous pulmonary venous return connection of the right lung to the inferior caval vein leading to the creation of a left-to-right shunt. "Scimitar syndrome, an anomalous venous return syndrome associated with MYRF mutations, may be misdiagnosed as isolated dextrocardia." (PMID 31048900, 2019). "Recent studies in human disease suggest that deleterious de novo variants in MYRF are associated with congenital diaphragmatic hernia, cardiac anomalies including Scimitar syndrome, urogenital anomalies, and an encephalopathy syndrome, consistent with expression in a range of tissues." (PMID 31048900, 2019). "Taken together, the unique association of CDH and similar non-diaphragm defects including CHD, Scimitar syndrome, genitourinal anomalies and sex reversal in 46XY patients with de novo variants in MYRF establish it as a new syndromic CDH gene." (PMID 30532227, 2018).
angle-closure glaucoma (2 papers, 2019 to 2020). The sudden increase of intraocular pressure, resulting in pain and an abrupt decrease in visual acuity. "Meanwhile, the association of angle-closure glaucoma with MYRF mutations is of special interest for future studies because the molecular basis of angle-closure glaucoma is largely unknown, although this condition is a common cause of blindness, especially in Asian populations." (PMID 31172260, 2019).
demyelinating disease (2 papers, 2013 to 2023). A broad group of disorders that affect the myelin sheaths that cover the neurons. "Gaining a detailed understanding of the downstream targets of MyRF is important as it could help with treatment of demyelinating diseases such as MS." (PMID 36730342, 2023). "Elucidation of the upstream pathways and signals that induce MYRF will be important both for understanding the molecular control of the myelination program, but also potentially for identifying strategies to promote remyelination in demyelinating disease." (PMID 23966833, 2013).
Pulmonary hypoplasia (2 papers, 2018 to 2023). "Furthermore, from clinical WES, we also identified a Swyer syndrome patient with a stop-gain variant in MYRF who had dextrocardia and pulmonary hypoplasia." (PMID 30532227, 2018). "Among MYRF variant carriers, four patients who did not have diaphragm defects developed pulmonary hypoplasia, further supporting common genetic control of these two processes." (PMID 30532227, 2018).
abdominal aortic aneurysm (1 paper, 2022). Enlargement and ballooning of the vessel that supplies arterial blood to the abdomen, pelvis and legs. "LUCAT1 acts as a decoy for miR-199a-5p and promotes MYRF expression, and lncRNA LUCAT1/miR-199a-5p/MYRF regulates the proliferation and apoptosis of SMCs in abdominal aortic aneurysms." (PMID 36093159, 2022).
Alzheimer disease (1 paper, 2019). A progressive, neurodegenerative disease characterized by loss of function and death of nerve cells in several areas of the brain leading to loss of cognitive function such as memory and language. "Missense variants in MYRF have been reported to have a significant association (p < 0.05) with late-onset Alzheimer’s disease." (PMID 31172260, 2019).
Anxiety (1 paper, 2025). Intense feelings of nervousness, tension, or panic often arise in response to interpersonal stresses. "Suggestive colocalisation was identified between TMEM258 and anxiety and between MYRF and depression (PP.H4 ≥ 0.6)." (PMID 40457327, 2025).
asthma (1 paper, 2023). "Through a TWAS analysis, five genes related to asthma were identified, including the MYRF gene which was also identified in colocalization analysis." (PMID 37875944, 2023).
Ataxia (1 paper, 2019). Ataxia refers to impaired coordination of voluntary muscle movement. "Mice with homozygous conditional knockout of MYRF in oligodendrocytes demonstrate severe tremors and ataxia from postnatal day 11, subsequently develop seizures, and die during the third postnatal week." (PMID 31172260, 2019).
demyelination (1 paper, 2019). "Studies in lysolecithin-induced demyelination animal models point to an essential role of MYRF in remyelination/myelin repair which is underlined by the observation that in chronic human MS lesions oligodendrocytes were found to lack MYRF expression." (PMID 33324887, 2019).
Dextrocardia (1 paper, 2019). The heart is located in the right hand sided hemithorax. "As such, dextrocardia in these individuals may represent a milder form of the cardiac anomalies present in syndromic patients carrying MYRF loss of function variants." (PMID 31048900, 2019).
glioma (1 paper, 2023). A benign or malignant brain and spinal cord tumor that arises from glial cells (astrocytes, oligodendrocytes, ependymal cells). "Further, the transcriptional regulators MYRF/C11ORF9 and SOX10, which are essential for the initiation and maintenance of myelination, were under-expressed in PM gliomas." (PMID 37055795, 2023). "In IDH-mutant/PM gliomas, coordinated hypermethylation in the transcription start site (TSS)/CpG island regions was observed in MO marker (GALC/O1), myelin components (MAG, MBP, MOBP, MOG), and essential regulators of the myelination program (MYRF/C11orf9 and SOX10)." (PMID 37055795, 2023).
hypoplastic left heart syndrome (1 paper, 2023). Hypoplastic left heart syndrome (HLHS) refers to the abnormal development of the left-sided cardiac structures, resulting in obstruction to blood flow from the left ventricular outflow tract. "This PTC is located next to the MYRF C-terminal domain, adjacent to two mutations detected in patients with hypoplastic left heart syndrome (HLHS)." (PMID 37584388, 2023).
Intellectual disability (1 paper, 2018). "Among patients with de novo damaging variants in MYRF, one individual with the R695H variant also had intellectual disability and delayed motor skills." (PMID 30532227, 2018).
lung carcinoma (1 paper, 2022). "We identified three genetic variants significantly associated with lung cancer risk: rs329118 in JADE2 (P = 8.80E−09), rs2285521 in GGA2 (P = 4.43E−08), and rs198459 in MYRF (P = 1.60E−06)." (PMID 35773316, 2022).
ovarian dysfunction (1 paper, 2026). The inability of the ovaries to function. "As more genetic and clinical information emerges about MYRF-OCUGS, recognizing this entity as a potential cause of 46, XY DSD (and possibly 46, XX ovarian failure) and the associated phenotypes becomes increasingly important." (PMID 41347118, 2026).
pancreatic cancer (1 paper, 2025). "MYRF has been identified as a target of miR-199b-5p, promoting pancreatic cancer progression." (PMID 40124684, 2025).
pancreatic ductal adenocarcinoma (1 paper, 2021). An infiltrating adenocarcinoma that arises from the epithelial cells of the pancreas. "Secondly, MYPF (MYRF) is an upregulated ER membrane-associated transcription factor in pancreatic ductal adenocarcinomas." (PMID 34917077, 2021).
X-linked adrenoleukodystrophy (1 paper, 2021). X-linked adrenoleukodystrophy (X-ALD) is a peroxisomal disorder resulting in cerebral demyelination, axonal dysfunction in the spinal cord leading to spastic paraplegia, adrenal insufficiency and in some cases testicular insufficiency. "In addition, in X-linked adrenoleukodystrophy patients, the combination of methylation levels of SPG20, UNC45A, and COL9A3 and also the expression levels of ID4 and MYRF would be a good marker for distinguishing the discriminating childhood from adult inflammatory phenotypes." (PMID 33691689, 2021).
tumor (5 papers, 2017 to 2025). "The tumor progression caused by miR-199b-5p inhibition is primarily related to its reduced binding to the MYRF protein." (PMID 40863724, 2025). "In the TCGA-NSCLC dataset, eight prognostic genes were significantly differentially expressed between tumor and normal tissues, with MYRF showing reduced expression and the remaining genes upregulated in tumors." (PMID 40124684, 2025).
cancer (4 papers, 2015 to 2025). A tumor composed of atypical neoplastic, often pleomorphic cells that invade other tissues. "The repressive effect from Tmem98 implies that mammalian MYRF can be regulated on the membrane in vivo, while the regulators are not necessarily expressed in cultured cancer cells." (PMID 33950834, 2021). "Well-differentiated secretory cancer cells contain a large quantity of MYRF, while MYRF is absent in poorly differentiated quasi-mesenchymal cells." (PMID 34917077, 2021). "While KIT mutations are well-known drivers of GIST, tissue-specific genes such as the serine/threonine protein kinase TESK1, the myelin regulatory factor MYRF, as well as the 5-oxo-L-prolinase OPLAH or the zinc influx transporter SLC39A9 have not been associated with cancer before." (PMID 26102504, 2015). "Although the roles of MYRF, CREG2, and NLRP10 in NSCLC have not been extensively studied, their involvement in other cancers has been documented." (PMID 40124684, 2025).
cardiovascular disease (1 paper, 2023). "In addition, it is known that ZDHHC5 is a palmitoyltransferase that modulates the activity of many proteins, some of them known cardiovascular disease-causing genes such as desmosomal cadherin desmoglein-2 (DSG2) and myelin regulatory factor (MYRF)." (PMID 37160609, 2023).
metabolic disorders (1 paper, 2021). "Consistently, the results revealed that dysregulation of MAG, HOXB3, MYRF and PLP1 led to metabolic disorders of sphingolipid and glutathione, which contributed to the pathogenesis of PD." (PMID 33325158, 2021).
MYRF also shares sentences with these, for which no sentence is quoted: infection (3 papers); diabetes mellitus (2); encephalitis (2); Huntington disease (2); multiple sclerosis (2); retinal degeneration (2); type 2 diabetes (2); Acute encephalopathy (1); aortic stenosis (1); aphakia (1); atrial septal defect (1); Atrophy (1); autoimmune disease (1); Blindness (1); brain injury (1); cerebral edema (1); depression (1); disorders of sex development (1); eye disorder (1); glaucoma (1); gonadal dysgenesis (1); hepatocellular carcinoma (1); Hyperglycemia (1); Hypertension (1); hypoxia (1); Kawasaki disease (1); muscle atrophy (1); myopia (1); nail-patella syndrome (1); neurodegenerative disease (1).
A further 8 diseases each share a sentence with MYRF in 1 paper.